MMP2 (matrix metallopeptidase 2)
Diseases named in the same sentence as MMP2 in open-access papers (continued):
Sharing a sentence is not in itself a finding about the gene and the disease.
osteosarcoma (continued). "We reported that knocking out of MMP‐2 gene considerably hinders osteosarcoma cell migration and inhibits doxorubicin‐induced cell migration." (PMID 38064181, 2023). "Recent findings reveal that MMP‐2 also localizes to different subcellular compartments, including the nuclei of osteosarcoma U2OS cells." (PMID 38064181, 2023). "High levels of zymogen precursors of MMP-2 and MMP-9 as well as active MMP-2 were found in most canine tumors, including osteosarcoma." (PMID 37048099, 2023). "We observed that aprepitant inhibited the migrative phenotype of osteosarcoma cells and reduced the expression levels and activities of matrix metalloproteinases (MMP-2 and MMP-9)." (PMID 36177059, 2022). "Competitive binding of lnc-SELPLG-2:1 to hsa-hsa-miR-10a-5p prevented BTRC from miRNA-mediated degradation, thereby activating the expression of VIM, MMP9, and MMP2, promoting osteosarcoma cell proliferation, migration, and invasion, and inhibiting apoptosis." (PMID 36199080, 2022). "Previous studies have revealed that SPAG5 silencing decreases matrix metalloproteinase-2 (MMP2) expression by downregulating FOXM1 to curb osteosarcoma (OS) cell invasion, migration, metastasis, and epithelial-mesenchymal transition (EMT)." (PMID 36118675, 2022). "We recently discovered that nuclear/nucleolar MMP-2 regulates ribosomal DNA genes and osteosarcoma migration." (PMID 36076910, 2022). "Accordingly, blockage of IGF-1R caused down-regulation of matrix metalloproteinase-2 (MMP-2) and MMP-9 and suppress migration of human osteosarcoma (OS) MG-63 cells." (PMID 36713521, 2022). "We recently examined MMP-2 in a designated subnuclear structure, the nucleolus, in osteosarcoma cells." (PMID 36076910, 2022). "Mounting evidence suggested that ZNF384 transactivated multiple downstream oncogenes, including HBO1 and MMP2, highlighting its tumorigenic function in osteosarcoma and colorectal cancer." (PMID 36100877, 2022). "We have recently identified MMP-2 as an N-terminal acetyltransferase substrate of Naa10p in osteosarcoma." (PMID 36433943, 2022). "Taken together, these results revealed that silencing of TTYH1 regulates the migration and invasion of U2OS osteosarcoma cells and reduces the expression of MMP2/9, N-cadherin, ZEB, and SNAIL." (PMID 35455021, 2022). "We also observed that aprepitant inhibited the migrative phenotype of osteosarcoma cells and reduced the expression levels and activities of matrix metalloproteinases (MMP-2 and MMP-9)." (PMID 36177059, 2022). "In osteosarcoma, NAA10 was directly associated with MMP‐2 protein through its acetyltransferase domain and maintained MMP‐2 protein stability via NatA complex activity." (PMID 35366056, 2022). "We suggested that the antimetastatic effect of aprepitant in osteosarcoma is probably attributed to its ability to modulate the transcriptional regulator, NF-κB, and subsequently, its target genes, including MMP-2, MMP-9, and VEGF-A." (PMID 36177059, 2022). "Our study revealed that cordycepin and cisplatin synergistically inhibited osteosarcoma cell invasion and invasion by downregulating MMP-2 and MMP-9 expression." (PMID 34953496, 2021). "Atorvastatin sensitizes the anti-cancer effect of cisplatin in human osteosarcoma by suppressing matrix metalloprotease 2 (MMP2) induced by cisplatin." (PMID 34065757, 2021). "Mechanistic exploration revealed that LINC01128 regulated MMP2 through sponging miR-299-3p and activation of Wnt/β-catenin signaling pathway in osteosarcoma." (PMID 34130697, 2021). "Increased B7-H3 expression is concurrent with pulmonary metastasis of osteosarcoma as its expression is associated with the diminished density of infiltrating CD8+ T lymphocytes and improved MMP-2 protein levels." (PMID 32902664, 2021). "CCN4 also promotes migration, invasiveness and metastasis of osteosarcoma cells upregulating MMP-2 and MMP-9 expression." (PMID 34228239, 2021).
osteosarcoma (continued). "In conclusion, their results demonstrated that curcumin exerts an inhibitory effect on osteosarcoma cell proliferation and invasion by inhibition of Notch-1 signaling, following the suppression of Hes-1, cyclin D1, MMP-2, and MMP-9 expression." (PMID 34671398, 2021). "It has been demonstrated that increased collagen I expression results in the activation of MMP2 in osteosarcoma cell lines, and MMP2 has been shown to promote osteosarcoma migration and invasion." (PMID 35145908, 2021). "Among them, MMP-2 and MMP-9 play a key role in initiating osteosarcoma cell metastasis and associate with poor response to chemotherapy in osteosarcoma." (PMID 34953496, 2021). "CCN2 promotes osteosarcoma cell migration by downregulating miR-519d and upregulating MMP-2 and MMP-3." (PMID 34228239, 2021). "Atorvastatin sensitizes the anti-cancer effect of doxorubicin and cisplatin in human osteosarcoma by suppressing matrix metalloprotease 2 (MMP2) induced by doxorubicin and cisplatin." (PMID 34065757, 2021). "The expression of MMP-2 (also known as gelatinase-A) promotes invasion and metastases of osteosarcoma cells." (PMID 32377334, 2020). "Osteosarcoma doxorubicin-resistance related up-regulated lncRNA (ODRUL) combines with miR-3182 to elevate matrix metalloproteinase 2 (MMP2) expression in osteosarcoma." (PMID 32429086, 2020). "Osteosarcoma cells proved to be sensitive to doxycycline exposure, as MMP-2 and MMP-9 secretion were suppressed in a dose-dependent manner." (PMID 32377334, 2020). "A previous study reported that TA3 attenuates the migration of MG63 osteosarcoma cells via the inhibitions of gelatinases (MMP-2 and MMP-9) via transcriptional suppression." (PMID 32774433, 2020). "Exosome treatment markedly increased COLGALT2, vimentin and MMP2/9 expression in the osteosarcoma cells." (PMID 32523950, 2020). "Triggered expression of RUNX2 by Wnt/B-catenin signaling was shown to promote the expression of several genes such as MMP1 and MMP2 that promote cell migration and metastasis in osteosarcoma by remodeling the extracellular matrix." (PMID 32695811, 2020). "In the experimental model of osteosarcoma cells, the inverse relationship between miR-328 and MMP-2 expression was found and inhibition of miR-328 resulted in the enhanced production of MMP-2." (PMID 32069846, 2020). "Among the 11 potential target genes, only MMP2 is reported to be closely related to the pathogenesis of osteosarcoma." (PMID 33108067, 2020). "The inhibition of MMP-2 and -9 by piperine also depended on the inhibition of Akt signaling pathways, as shown in breast, osteosarcoma, prostate, and fibrosarcoma cancer cells." (PMID 33256185, 2020). "Studies have shown that increasing B7-H3 expression subsequently increases the expression of MMP-2 in pancreatic cancer and osteosarcoma, consequently increasing the invasive capacity of these cells." (PMID 31382461, 2019). "Both MMP-2 and MMP-9 have been suggested as prognostic markers and associate with metastasis in osteosarcoma." (PMID 31418125, 2019). "In this way, Zhang & Zhang40 (2015) found MMP-2 involvement was higher in the individuals presenting osteosarcoma than in the control group." (PMID 31508793, 2019). "Our results showed that upregulated HMGN5 in a hypoxic environment increased the expression of c-jun and finally increased the expression of MMP2 and MMP9, which was associated with migration and invasion of osteosarcoma." (PMID 31930127, 2019). "To investigate the effects of BD on osteosarcoma invasive ability in vivo, we evaluated lung metastasis and detected the expression of MMP‐2 and MMP‐9 in different groups." (PMID 31631559, 2019). "Several studies have highlighted that the invasive capacities of osteosarcoma cells are correlated with MMPs expression, particularly MMP-2 and MMP-9." (PMID 31370265, 2019).
osteosarcoma (continued). "CTGF was recently shown to promote angiogenesis, increase MMP-2/3 expression and cell migration in osteosarcoma, whereas knockdown of CTGF reduced lung metastasis in an experimental mouse model." (PMID 31418125, 2019). "The expression of MMP-2 and MMP-9 is upregulated in osteosarcoma tissue and is associated with pulmonary metastasis and lower overall survival in patients with osteosarcoma." (PMID 30235848, 2018). "Overexpression of PKD1 inhibits osteosarcoma cell proliferation, invasion, and migration and reduced matrix metalloproteinase 2 (MMP2), while knockdown of PKD1 has the opposite effects." (PMID 30419840, 2018). "Coherent with this data we found that MMP2 gene expression level was higher in metastatic cell line than the other osteosarcoma cell lines." (PMID 30093974, 2018). "Coherently with other studies carried out on osteosarcoma cell lines, we observed that MMP2 was upregulated in all osteosarcoma cell lines especially in metastatic cell line." (PMID 30093974, 2018). "In osteosarcoma, studies indicated that the repression of MMP-2 and MMP-9 decreases the ability of osteosarcoma cells to migrate and invade." (PMID 30235848, 2018). "Based on these data, stromal ADSCs promote osteosarcoma progression by increasing STAT3 signalling-mediated MMP2/9 expression." (PMID 28423603, 2017). "To further confirm the role of FAK signaling in TSP1-induced osteosarcoma cell migration and invasion, we detected the MMP2, MMP9 and FN1 expression in Well5 and U2OS cells after FAK were silenced by siRNAs." (PMID 29100277, 2017). "Nobiletin inhibits human osteosarcoma cells motility, migration and invasion by down-regulating MMP-2 and MMP-9 expressions via ERK and JNK pathways." (PMID 28938584, 2017). "Suppression of ERK/MMP-2 expression contributes to Silibinin-inhibited cell migration and invasion in human osteosarcoma MG-63 cells." (PMID 29267213, 2017). "An upregulation of the NFAT-MMP-2 pathway had been also demonstrated in the development of metastatic osteosarcoma, where the secretion of active MMP-2 is under the transcriptional regulation of NFAT." (PMID 26822858, 2016). "Of all MMPs, MMP-2 and MMP-9 are most widely studied that both gain and loss-of function are associated with osteosarcoma progression." (PMID 27144433, 2016). "The present study sought to determine the anti-metastatic effect of nobiletin on the human osteosarcoma cells in vitro by monitoring the regulation of MMP-2 and MMP-9 expressions and the possible signaling pathways." (PMID 27144433, 2016). "In pancreatic adenocarcinoma cells, EFEMP1 activates AKT signaling in pancreatic carcinoma cell lines, and activates NF-κB signaling to promotes the migration and invasion of osteosarcoma via MMP-2 with induction by AEG-1." (PMID 27713911, 2016). "In osteosarcoma, B7-H3 promoted cell invasion and upregulated matrix metalloproteinase 2 expression (MMP-2)." (PMID 27145365, 2016). "Depletion of αv integrins in human SaOS-2 osteosarcoma cells through expression of an intracellular antibody suppressed MMP-2 expression and the induction of bone differentiation markers, implying that αv integrin regulates the osteosarcoma cell phenotype." (PMID 27409827, 2016). "Analysis of MMP expression and activity in osteosarcoma cell lines, biopsies and xenografts revealed a strong expression of MMP2 in culture supernatants from cell lines and in tumor xenografts while MMP9 expression was below the detection limit." (PMID 26979530, 2016). "We found a direct regulatory effect of EFEMP1 on MMP-2 expression and activity in osteosarcoma cells, and there was a strong correlation between EFEMP1 and MMP-2 expression in human osteosarcoma samples." (PMID 25987128, 2015).
osteosarcoma (continued). "We validated the link among EFEMP1, AEG-1 and MMP-2 in osteosarcoma patients using immunohistochemical staining." (PMID 25987128, 2015). "Further mechanistic studies showed that this MMP-2 inhibition was mediated by miR-328 up-regulation, treatment of osteosarcoma 143B and U2OS cells with resveratrol (RESV) for 6 h can up-regulate miR-328 expression by approximately 2-fold in both cell lines." (PMID 26305257, 2015). "Lower levels of the osteosarcoma metastasis-associated proteins CXCR4, MMP-2, MMP-7 and MMP-9 were detected in siEZH2 cells." (PMID 26265454, 2015). "Combining data from our miRNA screening profiles and miRNA target databases, we found that RESV treatment of osteosarcoma cells upregulated the expression of miR-328 which revealed the suppressive effects on MMP-2 and cell motility." (PMID 25605016, 2015). "Our previous data strongly suggest that AEG-1 plays a crucial role in osteosarcoma progression through MMP-2." (PMID 25987128, 2015). "Our previous study revealed that B7-H3 regulated invasion of osteosarcoma cells at least partly through MMP-2." (PMID 25908926, 2015). "This study characterized the antimetastatic effect of RESV on the inhibition of MMP-2 in human osteosarcomas, which is responsible for subsequent decreased migration, adhesion, and metastasis." (PMID 25605016, 2015). "Clinical samples indicated inverse expression between MMP-2 and miR-328 in normal bone and osteosarcoma tissues." (PMID 25605016, 2015). "The results showed that RESV suppresses the metastatic potential of human osteosarcomas through transcriptional and epigenetic regulation of MMP-2 by respectively inhibiting CREB-DNA-binding activity and upregulating miR-328." (PMID 25605016, 2015). "Results from IHC staining showed that the expression of MMP-2 in osteosarcoma patients was significantly higher than in normal bone tissues." (PMID 25605016, 2015). "Zymography assay demonstrated that halofuginone strongly reduces the activation of MMP-2 in osteosarcoma cells, a metalloproteinase that plays a crucial role in the cell invasion process." (PMID 26015407, 2015). "Knockdown of MMP-2 or MMP-3 expression via transfection with MMP-2 or MMP-3 siRNA abolished CTGF-induced osteosarcoma cell migration activity, meaning both MMP-2 and MMP-3 involved in CTGF-mediated cell migration." (PMID 25003330, 2014). "Actinomycin-D, cyclohexamide, retinoic acid, and dexamethasone inhibited MMP-2 and -9 in osteosarcoma cells." (PMID 24190483, 2014). "High CTGF expression was significantly associated with clinical stage and metastasis; higher CTGF and lower miR-519d expression were linked with MMP-2 and MMP-3 expression, correlating with osteosarcoma development and metastasis." (PMID 25003330, 2014). "Sensitivity to doxycycline and EGCG in normal osteosarcoma U2OS cells was nearly equivalent in MMP-2 secretion, but secretion of MMP-9 was significantly more sensitive to doxycycline than EGCG." (PMID 24190483, 2014). "Table III shows the quantitative densitometry results from the effects of natural inhibitors EGCG, the NM and retinoic acid on MMP-2 and -9 secretion by osteosarcoma and rhabdomyosarcoma cell lines." (PMID 24190483, 2014). "Osteosarcoma and rhabdomyosarcoma showed bands corresponding to MMP-2 and -9 with dose-dependent enhancement of MMP-9 with phorbol 12-myristate 13-acetate (PMA) treatment." (PMID 24190483, 2014). "We examined the effects of cytokines, mitogens, inducers and inhibitors on MMP-2 and -9 expression in osteosarcoma (U2OS) and rhabdomyosarcoma (RD)." (PMID 24190483, 2014). "In this study we investigated the effects of selected cytokines, inducers, and inhibitors affecting cancer cell metabolism on the regulation of MMP-2 and -9 activities in osteosarcoma and rhabdomyosarcoma cell lines." (PMID 24190483, 2014).
osteosarcoma (continued). "Table II shows the quantitative densitometry results from the effects of chemical inhibitors doxycycline dexamethasone, actinomycin-D and cyclohexamide on MMP-2 and -9 secretion by osteosarcoma and rhabdomyosarcoma cell lines." (PMID 24190483, 2014). "A significant negative correlation was found between NM modulation of Matrigel invasion inhibition and MMP-2 secretion with osteosarcoma U2OS (r=−0.835) and rhabdomyosarcoma RD (r=−0.675)." (PMID 24190483, 2014). "Table I shows the quantitative densitometry results from the effects of inducers PMA, TNF-α, IL-1β and LPS on MMP-2 and -9 secretion by osteosarcoma and rhabdomyosarcoma cell lines." (PMID 24190483, 2014). "Of the MMPs, MMP-2 is present in large quantities in cancer tissues, including human osteosarcoma, and accumulating evidence indicates that MMP-2 plays a critical role during tumor invasion and metastasis." (PMID 23940627, 2013). "A previous report showed that calpain 1 and calpain 2 were involved in the adhesive and invasive abilities of osteosarcoma cells by affecting MMP-2 secretion." (PMID 23855590, 2013). "Silibinin suppresses human osteosarcoma MG-63 cell invasion by inhibiting the ERK-dependent induction of MMP-2." (PMID 24278338, 2013). ", a traditional medicinal plant, possesses antimetastatic effects on human osteosarcoma cells by decreasing MMP-2 and MMP-9 secretions through p38 and Akt signaling pathways." (PMID 24278338, 2013). "U-2OS osteosarcoma cells showed strong bands corresponding to inactive MMP-2 and MMP-9 and faint bands corresponding to active MMP-2 and MMP-9 dimer; PMA treatment enhanced MMP-9 and MMP-9 dimer activity." (PMID 23900236, 2013). "Analysis revealed a positive correlation between u-PA and MMP-2 expressions of NM-treated osteosarcoma MNNG-HOS and between u-PA and MMP-2 and MMP-9 expressions of osteosarcoma U-2OS and rhabdomyosarcoma RD, as shown inTable II." (PMID 23900236, 2013). "In vitro, increasing expression of B7-H3 promotes osteosarcoma cell invasion, at least in part by upregulating matrix metalloproteinase-2 (MMP-2)." (PMID 23940627, 2013). "A significant negative correlation was found between NM modulation of Matrigel invasion inhibition and MMP-2 secretion with osteosarcoma MNNG-HOS (r=−0.6531), osteosarcoma U-2OS (r=−0.835) and rhabdomyosarcoma RD (r=−0.675)." (PMID 23900236, 2013). "In this study, we focused on the modulating effect of NM on the activities of MMP-2 and -9, TIMPs and u-PA in pediatric human sarcomas: osteosarcoma and rhabdomyosarcoma cell lines." (PMID 23900236, 2013). "On gelatinase zymography, osteosarcoma MNNG-HOS showed a band corresponding to MMP-2 and induction of MMP-9 with PMA (100 ng/ml) treatment." (PMID 23900236, 2013). "In our study, we found that B7-H3 regulated invasion of osteosarcoma cells at least partly through MMP-2." (PMID 23940627, 2013). "We found that MMP-2 protein levels were increased in B7-H3-transfected osteosarcoma cells, while the expression of MMP-2 was decreased after B7-H3 siRNA transfection in MG-63 cells compared with the vector controls." (PMID 23940627, 2013). "Osteosarcoma cell lines from F1 mice expressed intermediate levels of MMP-2 and NFAT and were invasive." (PMID 20107604, 2010). "The LM8 cell line, which was established from Dunn murine osteosarcoma, expresses MMP-2 and VEGF, possesses an extremely high metastatic potency, and has been used as an excellent tool for the study of inhibitory agents against pulmonary metastasis." (PMID 20170548, 2010). "In the present study, the MMP-inhibitor Marimastat significantly inhibited osteosarcoma cell invasion, which suggest that MMPs are vital factor in osteosarcoma invasion, and that risedronate suppressed the expressions of MMP-2 and MMP-9." (PMID 19624845, 2009). "Increased MMP-2 activity was also reported in colon carcinoma and in osteosarcoma cell lines after 5 Gy of radiation at short time periods of up to 24 h." (PMID 19323831, 2009).